STAT3 (signal transducer and activator of transcription 3)
Diseases named in the same sentence as STAT3 in open-access papers (continued):
Sharing a sentence is not in itself a finding about the gene and the disease.
malaria (11 papers, 2012 to 2026). Malaria is a serious and sometimes fatal disease caused by a parasite that commonly infects a certain type of mosquito which feeds on humans. "PTPRT is a tyrosine phosphatase receptor involved in STAT3 pathway and was recently reported to be associated with mild malaria susceptibility in Benin populations." (PMID 34868193, 2021). "Importantly, our bioinformatic analysis of a published RNAseq dataset suggests that STAT3 activation is one of the hallmark features in severe malaria patients with metabolic dysfunction." (PMID 40702267, 2025). "Our findings reveal a novel link between GR signaling, STAT3 activation, cytokine expression and glucose metabolism during severe malaria." (PMID 40702267, 2025). "This study shows that disease tolerance in malaria is mediated by glucocorticoid receptor (GR) signaling by limiting STAT3 activation, and identifies a potential therapeutic treatment for severe malaria." (PMID 40702267, 2025). "Collectively, these findings demonstrate that JAK/STAT3 inhibition with ruxolitinib effectively mitigates severe disease in two distinct experimental malaria models." (PMID 40702267, 2025). "Remarkably, hepatic Etv6 expression in response to both malaria and vaccination was very similar to that of Stat3, though the constitutive expression of Etv6 in the liver was only about 1/3 of that of Stat3, with approximately 58 above normalization level." (PMID 35214745, 2022). "We found that primaquine and CQ, which are malaria drugs, induce apoptosis through the nEGFR/Stat3 complex and c-Myc downregulation." (PMID 34884765, 2021). "Our data indicate that Heme/HO-1, CXCL10/CXCR3 and STAT3 molecules as well as related signaling pathways play very important roles in the pathogenesis of severe malaria." (PMID 22479586, 2012). "Taken together, our data indicate that Heme/HO-1, CXCL10/CXCR3 and STAT3 molecules as well as related signaling pathways play very important roles in inflammation and organ damage in the pathogenesis of severe malaria." (PMID 22479586, 2012). "Therefore, STAT3 is a key player regulating protection and the cytokine plasticity of memory T cells in malaria." (PMID 32634740, 2020). "Since NF-κB is a well established signaling pathway which contributes to the initiation and development of malaria, we hypothesize that STAT3 may plays an important role in the pathogenesis of severe malaria." (PMID 22479586, 2012). "Given the persistent activation of STAT3 and the emergence of hypoglycemia during treatment, it is highly important to investigate whether co-administration of ruxolitinib with anti-malarial drugs could improve survival in Plasmodium-infected mice and malaria patients." (PMID 40702267, 2025). "The findings provide mechanistic insight into posttranslational regulation of STAT3 in Tfh cell development and function, which broadens our understanding of the molecular regulation of effector CD4+ T cell responses in blood-stage malaria." (PMID 39024388, 2024). "STAT3 hyperactivation has also been observed in other lethal experimental malaria models, and IL-6, a key upstream activator of STAT3, is significantly elevated in severe malaria patients compared to those with non-severe malaria." (PMID 40702267, 2025).
mantle cell lymphoma (11 papers, 2013 to 2025). Mantle cell lymphoma is a rare form of malignant non-Hodgkin lymphoma affecting B lymphocytes in the lymph nodes in a region called the ``mantle zone''. "In mantle cell lymphoma (MCL), STAT3 mutations, although rare, can lead to constitutive activation of the JAK/STAT pathway, promoting tumor cell survival, proliferation, and immune evasion." (PMID 41438753, 2025). "CK2 positively regulates STAT3- and NF-κB-dependent signaling in mantle cell lymphoma." (PMID 40643484, 2025). "A 2021 study found that Tucidinostat induces apoptosis in DLBCL cells by targeting the HDACs/STAT3/Bcl-2 pathway, while Abexinostat has proven effective in relapsed or refractory follicular lymphoma (FL) and mantle cell lymphoma (MCL)." (PMID 40299416, 2025). "Interestingly, STAT-3 expressions were present in all three cases of mantle cell lymphomas (MCL) and three out of four primary mediastinal large B cell lymphoma (PMBL) cases." (PMID 37175040, 2023). "Moreover, Tiper and Webb also demonstrated that Trichostatin-A, a pan-HDACi enhanced both CD1d- and MHC class II-mediated antigen presentation in mantle cell lymphoma (MCL), as well as inhibiting STAT3-regulated inflammatory cytokine secretion by MCL cells." (PMID 37808081, 2023).
metastatic colorectal cancer (11 papers, 2015 to 2024). "A clinical trial is currently underway on a combination therapy for metastatic colorectal cancer comprising the STAT3 inhibitor napabucasin and PD-L1 inhibitor pembrolizumab (NCT02851004)." (PMID 35927628, 2022). "Taken together, our data suggest that compound 19 can be a novel therapeutic agent for metastatic colorectal cancer by concurrently targeting STAT3 and NF-κB signaling pathways." (PMID 31360301, 2019). "Our data suggest that Akt, STAT3, AMPKα and Bad activation can be biomarkers for metastatic colorectal cancer." (PMID 26258407, 2015). "Moreover, the efficacy of combinations of chemotherapeutic drugs and napabucasin, a small-molecule STAT3 inhibitor, have been assessed in various clinical trials, including those involving patients with metastatic colorectal cancer (CRC)." (PMID 30109144, 2018). "Indeed, siRNA silencing of STAT3 combined with oxaliplatin therapy, in mouse models of metastatic colorectal cancer (HCT116), was previously found to reduce tumor size better than either drug separately." (PMID 29898900, 2018). "Overcoming FTD-activated ERK/AKT/STAT3 signaling provides a compelling rationale for testing and optimizing the combination strategy with TAS102 plus regorafenib against metastatic colorectal cancer." (PMID 38953895, 2024). "We have shown that carcinoembryonic antigen cell adhesion molecule 1 long isoform (CEACAM1-L) expression in MC38 metastatic colorectal cancer (CRC) cells results in liver metastasis inhibition via CCL2 and STAT3 signaling." (PMID 29262644, 2017).
polycystic kidney disease (11 papers, 2013 to 2025). A usually autosomal dominant and less frequently autosomal recessive genetic disorder characterized by the presence of numerous cysts in the kidneys leading to end-stage renal failure. "We and others have shown that PC1-p30 is overexpressed in polycystic kidneys, targets to the nucleus and regulates the activities of several transcription factors including STAT3, STAT6, TCF and CHOP." (PMID 27560828, 2016). "In addition, others have reported that JAK2-STAT3 is activated in polycystic kidney disease (PKD) and STAT3 inhibitors like pyrimethamine could inhibit ADPKD cell proliferation and alleviate disease progression in Pkd1 mice." (PMID 39335615, 2024). "Stat3 was selected for this purpose because it is a well-defined gene with increased expression in ADPKD and in murine polycystic kidney disease models." (PMID 34611276, 2021).
polycythemia vera (11 papers, 2012 to 2025). "In polycythemia vera, the STAT3 pathway correlates with poorer prognosis and is constitutively active due to the presence of the JAK2 V617F mutation." (PMID 31399589, 2019). "Moreover, it has been previously demonstrated that transcription of the anti-apoptotic Bcl-2 protein is regulated by the STAT3/5 signaling pathway and that Bcl-2 is overexpressed in erythroid cells from patients with polycythemia vera." (PMID 22418850, 2012). "We already reported elevated plasma levels of IL-6 in patients with MPN and that IL-6 stimulated JAK2/STAT3 and AKT signaling in polycythemia vera (PV) and primary myelofibrosis (PMF)." (PMID 34206393, 2021).
prostate adenocarcinoma (11 papers, 2014 to 2025). "FOXQ1 expression activated the following pathways in prostate adenocarcinoma: the IL6/JAK/STAT3 signaling pathway, interferon–alpha response pathway, UV response pathway, apoptosis pathway, and allograft rejection pathway." (PMID 36118871, 2022). "A regulatory link of PKCε with STAT3 has also been established in prostate adenocarcinoma." (PMID 35047407, 2021). "As hIL6 activates the Janus kinase‐signal transducer and activator of transcription (JAK‐STAT) pathway, we examined the degree of phosphorylation of the signal transducer and activator of transcription 3 (STAT3) in an androgen‐sensitive human prostate adenocarcinoma (LNCaP) cell line." (PMID 30468023, 2019). "This suggestion is reinforced by the fact that the expression of LEP, leptin receptor (LEPR) and its main downstream signaling genes (JAK2, STAT3) is reduced in prostate adenocarcinoma, suggesting that this system is involved in the mechanism of apoptosis defense in proliferating tumor cells." (PMID 31671654, 2019). "Prostate adenocarcinomas developed in all mice transplanted with nontargeting (NT) sgRNA organoids but not in those in which either ERG or Stat3 was deleted." (PMID 40858905, 2025). "The prostate adenocarcinoma cell line PC3 is STAT3 negative, whereas DU145 has constitutively activated pSTAT3, most probably due to an autocrine production of IL6." (PMID 28636670, 2017).
retinal degeneration (11 papers, 2017 to 2025). Degeneration of the retina. "We also found that in miR-223-null CD11b+ cells from the retina, there was increased C1qa which is associated with progressive retinal degeneration, as well as increased Stat3, also associated with retinal disease." (PMID 32671067, 2020). "To confirm that the HT-induced pathology involves regulated pathomechanisms, we performed western blot analysis to assess the activity of the major signaling pathways ERK1/2, AKT, NFKB, and STAT3, which previously had been associated with various types of retinal degeneration." (PMID 37213216, 2023). "Through protein–protein interaction (PPI) network analysis, six hub ferroptosis-related genes (Jun, Stat3, Hmox1, Atf3, Hspa5 and Ripk1) are ultimately identified in a mice model of retinal degeneration induced by light damage." (PMID 40299661, 2025). "Other retinal degenerative models, transgenic RHO P347S and Prp2rds+/− (perpherin-2, retinal degeneration slow) mice, manifest similar p-STAT3 (Y705) levels in Müller glia, in addition to a weak immunoreactivity for p-STAT3 in photoreceptors." (PMID 36430227, 2022). "CNTF therapy enhances the protective properties of Müller glia through LIF/gp130/STAT3 signaling, thereby preventing retinal degeneration." (PMID 36389729, 2022). "In the past, efforts to rescue photoreceptors through manipulation of the STAT3 pathway in vitro or in vivo have produced encouraging results in animal models of retinal degeneration." (PMID 28767729, 2017). "Previous studies have shown that activation of STAT3 pathways in Müller cells promotes photoreceptor survival in retinal degeneration." (PMID 28767729, 2017). "In a mouse model of light-induced retinal degeneration, intravitreal delivery of LIF improved PR survival and retinal function by activating STAT3 in Müller glia and PR." (PMID 36389729, 2022). "It has been reported that the phosphorylation of signal transducer and activator of transcription 3 (STAT3) and ERK in Müller cells plays an important role in ciliary neurotrophic factor (CNTF)-mediated photoreceptor rescue in the retinal degeneration." (PMID 31179317, 2019). "Our results demonstrate that during RCS rats’ retinal degeneration, classically activated immune cells up-regulated JAK2/STAT3 pathway and produce persistent pro-inflammatory factors, but only transient anti-inflammatory factors in early stage." (PMID 31402855, 2019). "In our research, in vivo experiments demonstrated that the JAK2/STAT3 pathway became activated during degenerative period which was the same as research on retinal degeneration has shown that JAK2 and STAT3 proteins are involved in photoreceptor apoptosis, especially in rd1 mice model." (PMID 31402855, 2019).
schizophrenia (11 papers, 2011 to 2025). A major psychotic disorder characterized by abnormalities in the perception or expression of reality. "Most importantly, during inflammatory responses, IL-22 is upregulated in the brain and may increase the production of TNF-α, IL-6, and prostaglandins and induce STAT3, MAP-kinase, and JAK-STAT pathways, which all play a role in schizophrenia." (PMID 36256663, 2022).
acute respiratory distress syndrome (10 papers, 2018 to 2026). Progressive and life-threatening pulmonary distress in the absence of an underlying pulmonary condition, usually following major trauma or surgery. "Previous study found that vagus nerve stimulation played a protective role in acute respiratory distress syndrome by increasing STAT3 and regulating macrophage transformation." (PMID 35140609, 2021). "Interestingly, Tregs lack of Tim-3 are noted to repress the expression of p-STAT3, thereby attenuating the induction of M2 macrophages in acute respiratory distress syndrome (ARDS)-associated pulmonary fibroproliferation." (PMID 30189872, 2018).
adenomyosis (10 papers, 2018 to 2025). The growth of endometrial tissue inside the muscular wall of the uterine corpus. "That latter fact may suggest that, firstly, perioperative suppression of STAT3 could also be effective in reducing the risk of adenomyosis and, second, a complete elimination of the risk should require not only perioperative but also postoperative interventions." (PMID 35740240, 2022). "For instance, NF-κB/β-catenin, NF-κB/p65, NF-κB/Stat3, and NF-κB/apoptosis signaling are interconnected in the pathogenesis and treatment of adenomyosis." (PMID 39595579, 2024). "Curiously, though, patients with adenomyosis display distinct JAK2/STAT3 pathway states in various tissues." (PMID 39886033, 2024). "The downregulation of the JAK2/STAT3 pathway corresponded with the low expression of KLF4 in the endometrial tissue of adenomyosis." (PMID 39886033, 2024). "In general, the formation of adenomyosis lesions involves the activation of JAK2/STAT3, and the development of adenomyosis lesions can be inhibited by blocking this route." (PMID 39886033, 2024). "These insights underscore the potential of targeting the JAK2/STAT3 pathway—both its upstream and downstream components—as a strategy to slow adenomyosis progression." (PMID 39595579, 2024). "Furthermore, this review underscores the significance of continuous STAT3 activation in promoting adenomyosis and the intriguing hypothesis that KRAS mutations could potentially serve as biomarkers for treatment efficacy, opening doors to genetically guided therapies." (PMID 37834773, 2023). "The expression of p-STAT3 in the adenomyosis group was significantly lower than that in the control group, and there was a positive correlation between IL-10 and p-STAT3 protein levels in all the women examined." (PMID 30687738, 2018). "The expression levels of IL-10, HOXA-10, STAT3, and p-STAT3 in the endometrium of women with adenomyosis and controls were examined by means of western blotting and immunohistochemistry." (PMID 30687738, 2018). "As IL-10 induced HOXA10 expression through phosphorylation of STAT3, we further detected p-STAT3 and STAT3 protein expression in the endometria of women with adenomyosis and normal controls." (PMID 30687738, 2018). "Together, these immunological and physiological alterations underscore a coordinated disruption of uterine homeostasis in adenomyosis, prompting us to consider the underlying mechanisms by which IL6–driven inflammation and STAT3 modulation impair tissue growth and remodeling." (PMID 41298316, 2025). "The involvement of SCs in EMID-induced adenomyosis is supported by a recent study demonstrating that EMID induces the activation of signal transducer and activator of transcription 3 (STAT3) right after the injury, which persisted throughout the entire course of adenomyosis progression." (PMID 35740240, 2022). "However, the endometrial p(Y705)-STAT3 expression level was decreased by 50% in women with adenomyosis compared with that in normal controls (P<0.001), and the protein levels of p-STAT3 and IL-10 were positively correlated (r = 0.712, P < 0.01)." (PMID 30687738, 2018). "Furthermore, the positive staining for p(Y705)-STAT3 observed in both the glandular epithelial and stromal compartments was decreased in the adenomyosis samples compared with that in normal samples, as determined by immunohistochemistry." (PMID 30687738, 2018). "The p-STAT3 level was lower in the endometria of the women with adenomyosis." (PMID 30687738, 2018). "We speculate that dysregulation of the IL-10/p-STAT3/HOXA10 signaling pathway results in embryo implantation failure in women with adenomyosis." (PMID 30687738, 2018). "According to our analysis, endometrial decidualization problems in patients with adenomyosis are brought on by aberrant pathways in the endometrial stromal cells of adenomyosis, including PI3K/Akt, JAK2/STAT3, and hedgehog." (PMID 39886033, 2024).
adenomyosis (continued). "However, adenomyosis disrupts this equilibrium, where an increase in IL-6 levels leads to the activation of the JAK2/STAT3 pathway, fostering EMT and enhancing cellular invasion capabilities." (PMID 39595579, 2024). "In this study, we demonstrated reduced IL-10, p-STAT3, and HOXA10 expression in the endometrium of adenomyosis patients, which might lead to impaired embryo implantation." (PMID 30687738, 2018). "Therefore, STAT3, VIM, VEGFA and HSP90B1 that were also annotated in interleukin-4 and interleukin-13 signalling in the present GSEA need to be validated to verify potential downregulation of this pathway in women with adenomyosis." (PMID 32933042, 2020). "Therefore, we further detected p-STAT3 expression in endometria from women both with and without adenomyosis." (PMID 30687738, 2018). "Although we did not detect sustained Stat3 mRNA elevation—likely due to negative feedback by SOCS3 —the persistent Il6 mRNA overexpression suggests that post-transcriptional activation of STAT3 or alternative pathways (e.g. MAPK) may underlie lesion progression in adenomyosis." (PMID 41298316, 2025).
allergic rhinitis (10 papers, 2020 to 2026). Inflammation of the nasal mucous membranes caused by an IgE-mediated response to external allergens. "Separately, intranasal BG administration (3–30 mg/kg) effectively ameliorated PM2.5-induced combined allergic rhinitis and asthma syndrome through the suppression of STAT3 and MAPK activation." (PMID 41156471, 2025). "In a mouse model of ovalbumin-induced allergic rhinitis, miR-199 is significantly elevated and is involved in the pathogenesis of autosomal recessive disorder disease through the miR-199-3p-Dnmt3a-STAT3 signaling pathway." (PMID 36200021, 2022). "It has been shown that inhibition of Wnt/β-catenin and JAK1/STAT3 signalings could suppress the development of allergic rhinitis." (PMID 34315133, 2021). "Thus, further study is needed to investigate whether YJD could alleviate allergic rhinitis via regulating Wnt/β-catenin or JAK2/STAT3 signaling pathways." (PMID 34315133, 2021).